CD4 (CD4 molecule)
Diseases named in the same sentence as CD4 in open-access papers (continued):
Sharing a sentence is not in itself a finding about the gene and the disease.
HIV-1 infection (continued). "Activation of CD4+ T cells facilitates HIV-1 infection; however, whether there are minimal signals required for the establishment of infection, replication, and latency has not been explored." (PMID 31116788, 2019). "In this sense, it has been recently reported that CD4+ T cell subsets have distinct transcriptional profiles that are related to the level of HIV-1 infection and might modulate the response to external stimulus." (PMID 31425551, 2019). "Furthermore, we discovered that CECs do not require cell-cell interactions but via soluble factors enhance HIV-1 infection/replication in autologous CD4+ T cells." (PMID 31772057, 2019). "- HIV-1 infection disrupts IL-7/IL-7R signaling and CD4+ T cell memory formation." (PMID 31507594, 2019). "Further studies may be designed to test shorter coculture periods than 1 week and/or investigate the association of HIV-1 infection with factors that regulate the expression of CD3, CD4, CD7, and CD34." (PMID 30761146, 2019). "Additionally, the impact of HIV-1 infection on the capacity of CD4+ T cells to express DNAM-1 ligands is controversial." (PMID 31366013, 2019). "Indeed, previous researches had shown that disruption of co-receptor CXCR4 and HIV-1 provirus by SaCas9/gRNAs promoted human primary CD4+ T cells and Jurkat T cells resistance to HIV-1 infection." (PMID 31186067, 2019). "Next, we checked the HDAC10 expression changes upon HIV-1 infection in primary CD4+ T cells." (PMID 31888084, 2019). "Further experiments are however warranted to know whether we could also counteract CD4 T-cell defective function during HIV-1 infection by specifically interfering with USP18 expression." (PMID 31658294, 2019). "Furthermore, when testing rω-1 and rκ5 in a Raji-DC-SIGN mediated capture transfer experiment, only rκ5 inhibited HIV-1 infection of CD4+ T-lymphocytes (p<0.001)." (PMID 31487324, 2019). "Taken together, our data clearly indicate that CD161+ CD4+ T cells are highly permissive for HIV-1 infection and that the reduced amount of these cells in infected individuals may be due to the death of the infected cells." (PMID 31594817, 2019). "For all participants the duration of infection is unknown, but given their asymptomatic conditions, relatively moderate viral loads and healthy CD4 T-cell counts, it is safe to assume that the participants have a chronic HIV-1 infection." (PMID 31492170, 2019). "Moreover, following HIV-1 infection in CD4+ T cells, various ISGs, including ‘common ISGs,’ were clearly upregulated." (PMID 30915053, 2019). "In addition, a recent report showed the dysregulation of the proteome of human CD4+ T cells in response to HIV-1 infection both in vitro and in vivo." (PMID 31608139, 2019). "To investigate whether HIV-1 infection affects CD161+ CD4+ T cells, we measured the percentage of cells expressing CD161 among CD4+ T cells from the blood or lymph node (LN) of HIV-1-negative and HIV-1-positive individuals receiving or not receiving ART." (PMID 31594817, 2019). "Moreover, CCR5-modified CD4+ T cells engrafted into humanized mice exhibited a significant survival and enrichment advantage after R5-tropic HIV-1 infection compared to unmodified cells." (PMID 31186067, 2019). "CECs via soluble mediators enhance HIV-1 infection/replication in CD4+ T cells." (PMID 31772057, 2019). "While the major viral reservoir in treated HIV-1 infection is comprised of CD4+ T cells, the distribution and characteristics of the monocyte/macrophage reservoir remain largely unknown." (PMID 31866988, 2019). "Since expanded CECs in HIV-infected individuals produce ROS, we reasoned these cells similar to the cord blood CECs might enhance HIV-1 infection in CD4+ T cells." (PMID 31772057, 2019). "We ectopically expressed TIM-1 on Affinofile cells and investigated whether expression of CD4 and/or co-receptors is necessary for HIV-1 infection when virus binding is mediated by TIM-1." (PMID 31638994, 2019).
HIV-1 infection (continued). "Here, we aimed to identify mechanisms that govern Meth enhanced HIV-1 infection of CD4+ T-cells." (PMID 30700725, 2019). "We may speculate that, during HIV-1 infection, CD4 T cell-derived EVs overexpressing miR-146b-5p behave as carriers of vasculoprotective effectors that prevent endothelial dysfunction at the onset of viral infection." (PMID 31311940, 2019). "FOXO1 inhibition makes resting CD4+ T cells permissive to HIV-1 infection." (PMID 31042779, 2019). "However, when we analyzed the CD4/CD8 ratio, both groups with recent HIV-1 infection presented lower CD4/CD8 ratios than the HIV-neg group after 6 and 12 months of cART." (PMID 30541557, 2018). "We focused on analyzing DEGs in the categories of cell death and survival, cell activation, cytokine/inflammation, and cell cycle regulation, corresponding to the observed differences in CD4+ T-cell death/survival and immune activation between SIVcpz and HIV-1 infections." (PMID 29615603, 2018). "Similarly, the p70-S6K1 is not only a critical regulator of transcription but also an inhibitor of autophagy, which reduces HIV-1 infection by selectively degrading Tat in primary CD4+ T cells." (PMID 29970186, 2018). "For example, the abundance of CD4+ T lymphocytes might provide more target cells for HIV-1 infection and transmission." (PMID 30524435, 2018). "In addition, this proinflammatory microenvironment, conditioned positively primary unactivated CD4+ T cells to HIV-1 infection." (PMID 29997630, 2018). "Activation of CD4+ T cells in early HIV-1 infection stage, therefore, may have a beneficial effect on CD4+ T cell homeostasis." (PMID 29636753, 2018). "We hypothesize that, in combination with antiretroviral drugs, a strategy to orchestrate CD4 T cell trafficking could contribute to a functional cure for HIV-1 infection." (PMID 29499057, 2018). "We also found that HIV-1 infection down-regulated CD4 expression in ILC1s, as observed in T cells." (PMID 29304123, 2018). "Furthermore, chronic HIV-1 infection activated and depleted both CD4+ and CD4- ILC1s, and impaired their cytokine production activity." (PMID 29304123, 2018). "In addition, simultaneous knockout of CXCR4 and CCR5, using one CXCR4/CCR5 combination sgRNA and CRISPR-SpCas9, was assessed in primary CD4+ T cells and showed an inhibition of dual tropic HIV-1 infection." (PMID 29337866, 2018). "Subsequently, since CD4 and MHC-I receptor downregulation during HIV-1 infection are associated with Nef-dependent subcellular trafficking events, we set out to investigate the trafficking pathways utilized by Nef proteins from these various reference strains and their subcellular localization." (PMID 30217018, 2018). "Professional antigen-presenting cells (APC; myeloid dendritic cells [DC] and macrophages [MΦ]; B lymphocytes) mediate highly efficient HIV-1 infection of CD4+ T cells, termed trans infection, that could contribute to HIV-1 pathogenesis." (PMID 29643243, 2018). "However, most studies to date have focused on studying exhaustion of CD8+ T cells, and to a less degree what role this process plays for CD4+ T cells in HIV-1 infection." (PMID 29403500, 2018). "In order to determine whether the virus obtained in the VOA culture supernatants of blood memory CD4 T-cell populations was infectious, we performed an in vitro HIV-1 infection assay." (PMID 29459864, 2018). "Therefore, ki67 is probably a better marker for CD4+ T cell decline in the setting of acute HIV-1 infection." (PMID 29636753, 2018). "Immunofluorescence confirmed that a significant fraction of the CCNT1 subunit of P-TEFb was localized to the cytoplasm, consistent with a previous observation that CCNT1 and CDK9 are detected in the cytoplasm in unstimulated resting memory CD4+ T cells, the target immune cells of HIV-1 infection." (PMID 29845934, 2018).
HIV-1 infection (continued). "Furthermore, CD4 T-cell count fell below 350/μl during the first 3 years of HIV-1 infection more frequently in individuals homozygous for Bw6 than in individuals homozygous for Bw4 (P = 0.013)." (PMID 30147699, 2018). "Also like in humans, antiretroviral treatment of HIV-1 infection results in systemic recovery of CD4 T cells in humanized mice." (PMID 29725337, 2018). "EVs released by CD4+ T cells mediate CD4-dependent inhibition of HIV-1 infection in vitro." (PMID 30364166, 2018). "In comparison to healthy donors, HIV-1 infection in treatment-naïve individuals was associated with elevated MFI of BDCA-2 (1.8 times, p = 0.015), CD32 (1.5 times, p = 0.046) and CD4 (1.6 times, p = 0.0013)." (PMID 29597250, 2018). "Therefore, a balance between activation and suppression of CD4+ T cells should be critical for controlling HIV-1 infection and is of great importance for HIV-1 vaccination and immunotherapy." (PMID 30524435, 2018). "We incorporated CD4+ T cells in our model as an essential part of studying HIV-1 infection." (PMID 29698393, 2018). "Since a significant proportion of ILC1s express CD4, the receptor for HIV-1 infection, we investigated whether HIV-1 can infect CD4+ ILC1s." (PMID 29304123, 2018). "HIV-1 infection depletes Exo1 levels in human CD4+ T cells in a Vpr-dependent manner." (PMID 30352932, 2018). "Importantly, upon entry into G1 phase, HIV-1 infection led to reduction of early and late RT products in activated CD4+ T and HeLa cells, depending on the presence of dephosphorylated SAMHD1." (PMID 29884836, 2018). "HIV-1 infection-induced CD32 expression in PHA/IL-2 activated CD4+ T cells." (PMID 30013105, 2018). "Finally, we investigated if preincubation with the supernatants derived from MDMs induced CD4+ T-cell activation differentially as it is known that the level of cell activation correlates with HIV-1 infection efficiency." (PMID 29997630, 2018). "Here the authors show that CD32 expression in CD4 T cells is associated with T cell activation, is up-regulated by HIV-1 infection and importantly does not appear to represent an enriched cellular niche for latent HIV-1." (PMID 30013105, 2018). "Therefore, we have identified the CD4+ ILC1 cells as a new target population for HIV-1 infection, and revealed that IFN-I contributes to the depletion of ILC1s during HIV-1 infection." (PMID 29304123, 2018). "at the time they acquired HIV-1 infection would have impaired antiviral immune response, thus leading them to progress twice as fast to a CD4 count less than 350 cells/μL or death than would people who had been free of schistosomes at time of HIV-1 seroconversion." (PMID 29965987, 2018). "In addition, we found that blocking the IFN-I pathway significantly decreased CD95 expression on CD4+ ILC1s in humanized mice with persistent HIV-1 infection." (PMID 29304123, 2018). "CD4 T cells in the LN are a major target for HIV-1 infection." (PMID 30081906, 2018). "Then, DCs are able to transfer these viruses to CD4+ T cells independently of viral replication through the formation of an “infectious” synapse, thus decreasing the efficiency of broadly neutralizing antibodies on HIV-1 infection of target T cells." (PMID 29515578, 2018). "Therefore, in this work we wished to establish the role of MATR3 in acute HIV-1 infection of CD4+ T lymphocytes and in reactivation from latency following LRA treatment in HIV+ aviremic patients’ cells." (PMID 30425153, 2018). "IP-10 binding CXCR3 and CD4+CXCR3+ T cells are the main targets of HIV-1 infection." (PMID 30541557, 2018). "In such a situation, it is intuitively appealing that increased trafficking of CD4 T cells could reduce their residency time in drug sanctuaries and contribute to a functional cure for HIV-1 infection." (PMID 29499057, 2018).
HIV-1 infection (continued). "Though several mechanisms have been proposed to account for this post-entry restriction to HIV-1, as in the case of resting memory CD4+ T-cells, a potential links between miRNA expression levels and the recalcitrance of monocytes to HIV-1 infection have been reported." (PMID 29510515, 2018). "The sole member of the type II IFN family, IFN-γ, is widely recognized for its role in macrophage activation, and it was recently shown to induce a potent, Env-dependent block to HIV-1 infection in CD4+ T cells that was distinct from that induced by type I IFN." (PMID 29764952, 2018). "Several mechanisms are thought to contribute to CD4+ T cell depletion in HIV-1 infection." (PMID 29636753, 2018). "In addition to U87 cells, we also tested the effect of IFITMs on HIV-1 infection of more physiologically relevant human CD4+ T cells and monocytes." (PMID 30087232, 2018). "HIV-1 infection is known to downregulate CD4 expression through internalization." (PMID 30026537, 2018). "Besides the miRNAs that appear to modulate HIV-1 infection by directly targeting the viral RNAs, certain miRNAs reportedly play an indirect role by regulating the expression of cellular cofactors in resting CD4+ T-cells." (PMID 29510515, 2018). "It has been observed for a long time that HIV-1 infection causes a decrease in IL-2 levels, which is one of the causes of CD4+ T cell depletion, but the mechanism was not clear." (PMID 29426337, 2018). "The increased gene expression observed in eEC potently inhibited HIV-1 infection of CD4+ T cells." (PMID 28839349, 2017). "Our findings confirm and/or identify novel HIV-1- and microbe-induced molecular pathways that may regulate HIV-1 infection, CD4+ T cell depletion, and immune dysregulation inside and outside the context of microbial translocation in the intestinal mucosa." (PMID 28241075, 2017). "This type of intracellular immunization has potential for use in treating HIV-1 infected individuals through stem cell genome editing approaches wherein all subsequently progeny CD4+ T cells will express the anti-viral VH and thus would be impervious to continued HIV-1 infection." (PMID 29203900, 2017). "Persistent latent reservoir in resting CD4+ T cells is a major obstacle in curing HIV-1 infection." (PMID 29192216, 2017). "Besides modulating CD4 expression in activated macrophages and bystander macrophages during HIV-1 infection, miR-221 and miR-222 participate in the phenotypic changes of monocyte/macrophage differentiation." (PMID 29301198, 2017). "A 54-year-old male, diagnosed with HIV-1 infection 8 years earlier, was well controlled on Atripla (efavirenz 600 mg/emtricitabine 200 mg/tenofovir disoproxil 245 mg) with CD4 count 370 cells/mm3 and viral load <40 copies/ml presented with fever, weight loss and shortness of breath." (PMID 28344518, 2017). "Over the years, a number of groups have studied CD4 CTL during different stages of HIV-1 infection." (PMID 28167943, 2017). "We cannot exclude the possibility that astrocytes in situ exposed to the neural tissue environment may be induced to express CD4 and CCR5 and therefore, along with endogenous CXCR4 expression, be susceptible to HIV-1 infection in vivo." (PMID 28178524, 2017). "However, during HIV-1 infection in vivo, activated CD4+ T-cells and macrophages are infected due to phosphorylation of SAMHD1." (PMID 29176984, 2017). "However, the effects of simultaneous genome editing of CXCR4 and CCR5 by CRISPR-Cas9 in blocking HIV-1 infection in primary CD4+ T cells has been rarely reported." (PMID 28904745, 2017). "Thus, CD4 mimetics holds the promise of therapeutic utility in preventing and controlling HIV-1 infection." (PMID 28529952, 2017). "Multivariable analysis showed that HIV-1 infection is independently associated with CD4 T cell activation and T cell exhaustion but not with terminally differentiated T cells (CD57+ and CD27−CD28−)." (PMID 28806406, 2017).
HIV-1 infection (continued). "Moreover, we showed that transducing AAV6 expressing SaCas9/sgRNAs in primary CD4+ T cells confers protection to HIV-1 infection." (PMID 29141633, 2017). "For therapeutic propose, the first description of CD4-Fc fusion protein showed the inhibitory activity against the formation of syncytia during HIV-1 infection in 1989, which showed the proof-of-concept of use of therapeutic Fc-fusion proteins for treatment of HIV-1 infection." (PMID 29375551, 2017). "On the other hand, IFN-I induces apoptosis of uninfected CD4+ T cells in peripheral blood and in secondary lymphatic tissue by upregulating TRAIL expression on CD4+ T cells, leading to the destruction of lymph node in gastrointestine in the acute phase of HIV-1 infection." (PMID 29163506, 2017). "The therapeutic potential of CD4+ CTL may be exploited also for vaccination purposes against HIV-1 infection, since these effectors are able to efficiently recognize and kill infected APC like macrophages, which constitute long-lived viral reservoirs." (PMID 28289418, 2017). "However, we identified a CD4+ T cell population with low levels of intracellular CD2 and high HIV-1 infection rates in comparison to CD4+ CD2+ cells." (PMID 28953327, 2017). "In HIV-2 infection, intracellular Nef promotes the downregulation of the T-cell receptor complex in CD4+ T-cells, whereas in HIV-1 infection, Nef seems to have lost its ability to downmodulate the expression of CD3–TCR complex on the surface of infected T-cells." (PMID 28588579, 2017). "Therefore, it was highly likely that activated CCR5+Ki-67+CD4+ T cells would be found in LT following HIV-1 infection." (PMID 28553284, 2017). "In addition, it has also been shown that IFNR blockade causes downregulation of cell-death signal cascades by the reduction in Bak expression and Fas-mediated apoptosis in CD4 T-cells using an in vitro HIV-1 infection model." (PMID 29301196, 2017). "Moreover, the authors reported that surface expression of CD57+ in cytolytic CD4+ T cells occurs early during acute HIV-1 infection, suggesting their involvement in the initial stages of HIV-1 acquisition." (PMID 28289418, 2017). "Thus, CD4+CD70+ T lymphocytes appear to have a role in increased B cell activation during HIV-1 infection [reviewed in Ref." (PMID 28473831, 2017). "Our data suggest that the gut CD4+ T cell response to microbes may contribute to the enhanced type I IFN responses in mucosal tissues of individuals with early HIV-1 infection." (PMID 28241075, 2017). "We now know that characteristic increases in germinal centers (GC) in lymphoid tissue (LT) during SIV and HIV-1 infections are associated with an increase in CXCR5+PD-1high Tfh, which expand to a large proportion of memory CD4+ T cells in LT, and are presumably specific for SIV or HIV epitopes." (PMID 28553284, 2017). "However, HIV-1 infection affected numbers of memory and regulatory CD4+ T cells and monocyte–macrophages with limitations made on broad numerical cell comparisons." (PMID 28279181, 2017). "Interestingly, HIV-1 infection triggered a significant increase in granzyme A, B and H expression in LP CD4+ T cells, which we confirmed at the protein level by flow cytometry." (PMID 28241075, 2017). "We postulate that several features of the LPAC model that distinguish it from standard HIV-1 infection of PBMCs may have contributed to the differences in gene expression between blood and gut CD4+ T cells." (PMID 28241075, 2017). "HIV-1 infection of microbe-exposed LP CD4+ T cells stimulated 3.4-fold higher levels of IL26, a Th17-derived cytokine that has antibacterial properties, and 3.0-fold higher levels of the IL23R, which acts as the receptor of IL23 and helps maintain Th17 cell function." (PMID 28241075, 2017). "They attributed this to the resting status of peripheral blood-derived CD4+ T cells, which could be overcome by coculture with lymphoid-derived cells, resulting in pyroptosis on HIV-1 infection." (PMID 29056936, 2017).